TLR2 (toll like receptor 2)
Diseases named in the same sentence as TLR2 in open-access papers (continued):
Sharing a sentence is not in itself a finding about the gene and the disease.
tumor (continued). "High mobility group box 1 (HMGB1) was expressed on HCC-derived exosomal membranes and bound with high affinity to Toll like receptor-2 (TLR-2), TLR-4, TLR-9 and advanced glycation end products (RAGE), which led to tumor cell survival, expansion and metastasis." (PMID 30897788, 2019). "Based on bioactivity screening, we devise a glucomannan polysaccharide with acetyl modification at a degree of 1.8 (acGM-1.8), which specifically activates toll-like receptor 2 (TLR2) signaling and consequently induces macrophages into an anti-tumor phenotype." (PMID 31118418, 2019). "Later, researchers identified an endogenous TLR2 agonist called high-mobility-group box 1 (HMGB1), wich is released by dying tumor cells as a result of tumor cell killing." (PMID 31240216, 2019). "Here, the synergistic effect of a TLR2-neutralizing antibody and a TLR9 agonist CpG ODN was observed to advance coherent immunotherapy against tumor metastasis." (PMID 31508424, 2019). "We evaluated TLR2, TLR4 and TNF-α mRNA expression in peritoneal macrophages and serum TNF-α protein levels at a single time-point after tumor induction and after therapeutic intervention with zymosan." (PMID 29588627, 2018). "We and others have observed that while normal oral squamous epithelium is relatively unresponsive to TLR stimuli, TLR2 and TLR4 ligands often induce SCC cells to make pro-tumor factors, such as IL-6, IL-8, VEGF, CCL2." (PMID 29467931, 2018). "Although CIS therapy was more effective than P-MAPA in reducing tumor growth, P-MAPA immunotherapy significantly increased the expressions of TLR2 and TLR4." (PMID 29343281, 2018). "Mice were CO2-euthanized and serum TNF-α level, TLR-2 and TLR-4 expression in peritoneal macrophages and tumor growth measured." (PMID 29588627, 2018). "Although CIS therapy was more effective than P-MAPA in reducing the tumor size, P-MAPA immunotherapy significantly increased the expressions of TLR2 and TLR4." (PMID 29343281, 2018). "Further studies are required to investigate the mechanisms how TLR2 incorporation promote CAR T cells to infiltrate into tumors and disrupt tumor microenvironment, which are the major challenges for treating CNS and extramedullary leukemia." (PMID 29458388, 2018). "Mechanically, CTC-derived ligands for TLR2 and TLR4 (TLR2/4) induced the systemic inflammation, thus increasing the production of proinflammatory cytokines such as G-CSF and IL-6 that could induce the conversion of neutrophil function from tumor-suppressing to tumor-promoting." (PMID 28415700, 2017). "The target tumor cells were added to BMDMs activated by the following TLR agonists; TLR1/2 agonist Pam3, TLR2/6 agonist LTA, TLR3 agonist poly(I:C), TLR5 agonist flagellin, TLR7 agonist CL264, and TLR9 agonist CpG." (PMID 29123526, 2017). "Although M1 macrophages has anti-tumor function, our data shows markers including CD68, CD86, TLR2 and TLR4 are correlated with CD163 too." (PMID 29152078, 2017). "In some tumor types, TLRs promote tumor proliferation and survival, as seen with TLR9 agonists, Pam2 lipopeptides (TLR2/6 ligands), and flagellin." (PMID 27708223, 2016). "PaCaDD135 tumor cells expressed predominantly TLR9 and to a lesser extent TLR2 and -4 (77.0%, 12.1% and 1.4% respectively) (bottom)." (PMID 27941651, 2016). "Tumor-derived versican (a proteoglycan which sequesters chemokines and acts as a chemo-attractant for inflammatory cells in the tumor milieu) can stimulate resident macrophages to secrete IL-6 and TNF-α in a TLR-2 dependent manner." (PMID 26608647, 2015). "For instance, activation of TLR2 and TLR6 in macrophages enhances metastasis of tumor cells, wherein receptor activation is mediated by tumor cell-derived versican, an extracellular matrix proteoglycan that is up-regulated in many tumor cells." (PMID 25149452, 2014).
tumor (continued). "The mechanism by which TLR2 induces tumor suppression is thought to be mediated through tumor-derived HMGB1, which activates TLR2 in dendritic cells in the tumor microenvironment, leading to tumor regression." (PMID 25309546, 2014). "Further complicating the issue is the fact that specific family members, such as TLR2, TLR4, and TLR9, following detection of corresponding TLR agonists, have a tumor promoting role in the biology of these tumors." (PMID 25411122, 2014). "TLR2 and TLR4 immunoreactivity was present mainly in the tumor-infiltrating inflammatory cells (lymphocytes), which were morphologically identical to monocytes/macrophages." (PMID 25547486, 2014). "The expression of miR-143 was significantly lower in 4 CRC cells with high TLR2 expression levels, especially in the poorly differentiated tumour cells SW620 and HCT116, showing that miR-143 levels are inversely correlated with the levels of TLR2 expression." (PMID 23866094, 2013). "We show that DC/tumor activated with combined TLR2 and TLR4 are most effective inducer of MUC1-specific CTL activation compared with solitary TLR2- or TLR4-activated DC/tumor on a per fusion cell basis." (PMID 23555011, 2013). "Blockage of versican V1 by shRNA knockdown, in tumor cells, inhibited TLR2/6, VDR, Cyp24, Cyp27B1, and hCAP18/LL-37 induction, as well as tumor cell proliferation and invasiveness." (PMID 23424670, 2013). "We also found that miR-143, a putative tumour suppressor that is down-regulated in CRC tissues, reduces the invasion and migration of CRC cells primarily via TLR2." (PMID 23866094, 2013). "TLR2 knockout mice exhibited significantly greater survival than WT mice after LLC inoculation and their lungs contained fewer and smaller tumor nodules." (PMID 23284890, 2012). "Of note, versican also binds to TLR-2 and acts as an agonist for the receptor to activate tumor-infiltrating myeloid cells by increasing production of cytokines, like TNF-α, to promote tumor metastasis." (PMID 24213471, 2012). "In our model, the increase in tumor multiplicity in TLR2-deficient mice, particularly in the proximal colon where there is the highest concentration of TLR2 and bacteria, indicates that a pivotal source of inhibition during inflammation is withdrawn when TLR2 is not present." (PMID 20885960, 2010). "Interestingly, ligation of TLR2 by versican appears to be directly involved in the activation of multiple types of cells in tumour stroma, including macrophages, and the induction of inflammatory cytokine secretion to generate an inflammatory microenvironment hospitable for tumor progression." (PMID 20871832, 2010). "Once the tumor cell releases these HSPs, the host's antigen presenting dendritic cells, can take up these antigens via the CD14, CD91, TLR2 and 4 receptors." (PMID 19247476, 2009). "Additionally, lipid peroxides generated during ferroptosis are recognized by Toll-like receptor 2 (TLR2) on macrophages, triggering phagocytosis and tumor antigen presentation." (PMID 41510171, 2026). "Moreover, BGN's activation of innate immune receptors such as TLR2 and TLR4 further underscores its potential as a universal modulator of tumor immunity." (PMID 41328346, 2026). "First, to test whether TLR2 is involved in tumor growth and MΦ polarization in mice, LLC-GFP were subcutaneously implanted in WT and TLR2−/− mice, and tumor growth and MΦ polarization were monitored." (PMID 39941817, 2025). "Additionally, in macrophages within the tumor microenvironment, CNPY3 is essential for TLR2 trafficking, playing a crucial role in preventing phospholipid peroxidation-induced resistance to ferroptosis." (PMID 40055606, 2025). "Although the tumor cells universally expressed various levels of TLR2, knockdown of TLR2 expression in B16F10 tumor cells did not affect the antitumor response in SUP3-treated mice." (PMID 41291775, 2025).
tumor (continued). "Further assessment demonstrated that the expression of necroptosis-related genes, including FADD, MLKL, TLR2, PGAM, HMGB1, CXCL 1, TRAF2, and EZH2, was elevated in tumor tissue, while FAS, RIPK1, RIPK3, TLR3, TNFRSF, ALDH2, and NDRG2 were upregulated in normal intestinal tissues." (PMID 40959081, 2025). "For example, TLR2 activation in nonimmune cells—such as tumor cells or endothelial cells—by endogenous ligands can promote tumorigenesis." (PMID 41291775, 2025). "The selective TLR2 inhibitor CU-CPT22 effectively blocked DAMP-induced signaling (e.g., HMGB1 release after chemotherapy), synergizing with DOXO to suppress tumor growth, reduce CSC frequency, and remodel the TME by decreasing Tregs and MDSCs while enhancing CD8+ T cells and M1 macrophages." (PMID 41375047, 2025). "TLRs regulate host defense mechanisms, elicit pro-tumorigenic responses, and could be deemed potential biomarkers to monitor tumor progression, specifically TLR4 in tumor survival and chemoresistance, and TLR2 in metastatic progression." (PMID 40809181, 2025). "The BCG cytoplasmic membrane is composed of a plasma membrane surrounded by lipid-attached peptidoglycan (PG) and arabinogalactan (AG), which are agonists of TLR2 and TLR4 and can be used as an adjuvant for tumor vaccines to enhance the maturation and migration of DCs in the tumor microenvironment." (PMID 40284501, 2025). "Additionally, TLR2, a pattern-recognition receptor (PRR), links tumor biology to the immune system by modulating inflammation and shaping the TME." (PMID 41375047, 2025). "Furthermore, we investigated the paracrine activation of dendritic cells (DCs) by UNE-C1 via TLR2 signaling, which primes a CD8+ T cell response essential for tumor regression." (PMID 39669578, 2024). "As the tumors express TLR2 and the normal tissue does not, the slow tumor clearance likely corresponds to receptor mediated tumor cell uptake (55 hours half-life)." (PMID 39320054, 2024). "While some TLRs, such as TLR2 and TLR4, have shown both promotive and suppressive effects on tumor growth, others like TLR3 and TLR5 offer promising avenues for therapeutic intervention due to their more defined roles in enhancing anti-tumor immunity." (PMID 38903515, 2024). "By focusing on toll-like receptor 2 (TLR2) on macrophages, 1-steaoryl-2-15-HpETE-sn-glycero-3-phosphatidylethanolamine (SAPE-OOH) on the surface of ferroptotic cells works to transmit an eat-me signal, which directs phagocytosis and restricts the tumor growth." (PMID 39104526, 2024). "Interestingly, there was a significant correlation between TGF-β, IL-6, TLR-2 and TLR-4 in the primary CRC tumor and SPP1 expression by macrophages in the metastatic intrahepatic tumor." (PMID 39372792, 2024). "The authors observed that an increased number of tumor cells expressing TLR-2 correlated with a longer five year survival of the patients, suggesting that TLR-2 may play a role as a favorable prognostic factor in gastric cancer." (PMID 39451226, 2024). "It has been proposed that fungal toll-like receptors (e.g., TLR2/TLR9), especially when compounded by a cytokine storm, may shift the immune system into an activated tumor microenvironment stimulating antileukemic effects." (PMID 39011219, 2024). "Soluble forms of all TLRs were elevated in GC patients, with significant differences based on disease stage but not tumor type, except for serum TLR2, TLR4, and TLR9." (PMID 39451226, 2024). "On the other hand, immunomodulatory agonists for TLR2 and TLR9 can enhance tumor immunity." (PMID 38390872, 2024). "Tumor cell proliferation in TLR2−/− mice was not promoted because they lacked M2 macrophages while TLR4−/− mice displayed a reduced tumor cell proliferation in response to PepO treatment owing to PepO could prevent TLR4 deficient macrophages from tumor-promoting M2 phenotype." (PMID 37925462, 2023).
tumor (continued). "MHC class II expression is suppressed by TLR2 activation on microglia, limits CD4+ T cell-dependent antitumor immunity, diminishes the antigen presentation ability of microglia, and enhances the immunosuppressive profile of the tumor microenvironment." (PMID 37700840, 2023). "The acquisition of tumor antigen to CER-1236-activated T cells is accompanied by enhanced CER-1236 cross-presentation, as evidenced by the triggering of E7-specific TCR-T responses in a class I and TLR-2-dependent manner." (PMID 37194236, 2023). "However, reconstitution with bacteria from PDAC hosts leads to the activation of select TLRs (TLR2 and TLR5) in macrophages which contributes to PDAC tumor growth and innate and adaptive immune suppression." (PMID 37588093, 2023). "TLR2 was shown to be regulated by miR-143 which, when expressed, suppresses TLR2 activation, resulting in reduced invasion and migration of CRC cells and reduced tumor growth." (PMID 37112730, 2023). "In contrast to TLR2, TLR1 activation by RT has been shown to have tumor-promoting effects." (PMID 37112730, 2023). "We found that the Arf1‐ablated tumor cells released HMGB1, oxidized low‐density lipoprotein (oxLDL), and genomic DNA, which might together bind to co‐receptors complex of the CD36/TLR2/TLR6 on the dendritic cell surface." (PMID 37786300, 2023). "HMGB1 can activate TLR2 and TLR4 on dendritic cells (DCs) to initiate antigen presentation and cytokine secretion, activating antigen‐specific CD4+ T cells and CD8+ T cells to recognize and eradicate tumor cells." (PMID 37945630, 2023). "TLR2−/− macrophages slightly inhibited tumor growth and PepO-priming did not significantly alter this inhibition." (PMID 37925462, 2023). "Cell surface TLRs, including TLR1, TLR2, TLR4, TLR5, TLR6, and TLR10, can actively capture extracellular information, including tumor cell-released DAMPs or apoptotic cancer cell fragments, such as HMGB1, HSP, and S100, as well as extracellular vesicles containing changed cell components." (PMID 36911674, 2023). "Using animal models of tumor-induced angiogenesis, West and co-workers reported a decade ago that carboxy-ethyl-pyrrole (CEP), an oxidized lipid of endogenous origin (DAMPs), promotes TLR2-dependent angiogenesis." (PMID 35215131, 2022). "HSP72 and HSP105 on the TEX surface were found to induce DCs to produce increased IL-6 in a TLR2- and TLR4-dependent manner, which in turn promoted tumor invasion by increasing STAT3-dependent matrix metalloproteinases 9 transcription activity in tumor cells." (PMID 35163380, 2022). "TLR2 and TLR8-AS1 expression was increased in the majority of tumours, although TLR2 expression was decreased in LUSC (P0.001), LUAD (P0.001), PRAD (P0.001), BRCA (P0.001), and LIHC (P0.001), and TLR8-AS1 expression was specifically decreased in LUSC (P0.001) and PRAD (P0.001)." (PMID 35801728, 2022). "Note that the TLR2/4 pathway was enriched in the untreated control group (false discovery rate [FDR] = 0.108), likely representing the signals induced by the spontaneous tumor cell death." (PMID 35404390, 2022). "It's worth noting that TLR1, TLR2, TLR3, TLR7, TLR8, and TLR9 were adversely connected with RNAss in the majority of cancers, but favourably correlated with RNAss in a very small number of tumours (KIRC, MESO, LAML, CHOL, KICH and THYM)." (PMID 35801728, 2022). "Wu etc. have reported that Toll-like receptor 2 (TLR2) might affect the prognosis of TGCT, as well as be an indicator of immune function in the tumor microenvironment." (PMID 35575252, 2022). "A study showed that the inhibition of IL-18 through TLR2 alleviated mouse HCC progression, whereas deletion of the IL-18 receptor enhanced tumor growth once the IL-18 had tumor-suppressive effects by promoting tumor-infiltration T cells." (PMID 36289606, 2022).
tumor (continued). "Tumor cells can release HMGB1 into the local microenvironment, where HMGB1 interacts with several receptors, such as toll-like receptor 2 (TLR-2), TLR-4, TLR-9, and the receptor for advanced glycation end products (RAGE), which can lead to tumor cell survival, proliferation, and angiogenesis." (PMID 34617194, 2022). "Both TLR2 and TLR4 are expressed on the surface of innate myeloid cells, such as macrophages and dendritic cells, but also endothelial and epithelial cells, and are key initiators of the innate anti-tumour immune response." (PMID 36499361, 2022). "However, EDN has also been shown to signal through Toll-like receptor 2 (TLR2) expressed by dendritic cells, highlighting an additional potential mechanism for enhanced anti-tumor immunity." (PMID 35756626, 2022). "Consistently, the number and the size of tumor spheres decreased significantly by TLR2 siRNAs compared with the negative control." (PMID 33614649, 2021). "M-MDSC that receive TLR2 stimuli in combination with Th1 cytokine IFN-gamma become inducible nitric oxide synthase (iNOS)+ macrophages that impede proliferation of CD8+ T cells, thus compromising anti-tumor cytotoxicity." (PMID 35048056, 2021). "Expression of TLR2 and TLR4 in the hematopoietic compartment aids tumor development." (PMID 34032639, 2021). "BM chimera experiments, to distinguish the role of the hematopoietic versus the nonhematopoietic compartment, indicated that TLR2 and -4 expression within the former was required for optimal tumor growth." (PMID 34032639, 2021). "Other tumor stromal cells, such as fibroblasts and endothelial cells also respond to TLR ligands, most consistently those specific for TLR2 and TLR4, which contributes to inflammation, tissue remodeling, and angiogenesis, though studies of these functions in TME are limited." (PMID 35048056, 2021). "PAUF has been shown to be an endogenous ligand for TLR2 and TLR4, it activates the canonical signaling pathways of TLR2-tumor progression locus 2 (TPL2)/mitogen-activated ERK kinase (MEK)/extracellular signal-regulated kinase (ERK), but it fails to mediate TLR2-induced NF-κB activation." (PMID 34884547, 2021). "Examples of cytokines and growth factors induced by TLR2 and/or TLR4 in OSCC cells include IL-1, IL-6, GM-CSF, TNF-alpha, CCL2, CCL20, CXCL8, and VEGF, which contribute to the inflammatory environment, vascularization, and tumor cell properties." (PMID 35048056, 2021). "Our previous study has reported that Toll-like receptor 2 could augment both OXPHOS and glycolysis to promote tumor growth." (PMID 33446221, 2021). "The combination of a TLR2 agonist and GM-CSF exhibits cooperative effects on DC activation and modulates TAM populations in the TME, which subsequently promote antigen-specific T cell infiltration in the tumor." (PMID 34599024, 2021). "A role for nonhematopoietic cell TLR2 and -4 expression in supporting tumor growth was also noted, as tumors in DKO mice that received WT BM were smaller than tumors in WT mice that received WT BM." (PMID 34032639, 2021). "Activated TLR2 or TLR4 in OSCC can trigger the production of IL-6 and other STAT3-activating factors that then act in autocrine fashion on the OSCC receptors, which is another major cell-intrinsic pro-tumor benefit of TLR activity." (PMID 35048056, 2021). "Finally, in ovarian cancer, TLR2 expressed on CD44+/MyD88+ CSCs promotes their self-renewal and induces the secretion of pro-inflammatory cytokines, thus actively contributing to tumor repair following injury induced by surgery or chemotherapy." (PMID 33321934, 2020).